APLN (apelin)
Diseases named in the same sentence as APLN in open-access papers (continued):
Sharing a sentence is not in itself a finding about the gene and the disease.
myocardial infarction (continued). "Apelin/APJ signaling has been shown to be proangiogenic and provide beneficial outcomes in response to myocardial infarction in rats whereas apelin levels are reduced in diseased murine and human hearts, increasing their susceptibility to myocardial ischemia-induced damage." (PMID 24901703, 2014). "A disturbance of apelin expression contributed to a decrease in the p-Akt and p-ERK1/2 levels in myocardial tissue after myocardial infarction (MI)." (PMID 36986889, 2023). "These discrepant results may be due to the different patient populations (septic or non-septic; for example after myocardial infarction) and/or the different investigated apelin isoforms." (PMID 37510916, 2023). "Moreover, plasma apelin concentrations were depressed early after myocardial infarction, but did not correlate with the left ventricular function parameters." (PMID 37510916, 2023).
cardiac hypertrophy (45 papers, 2010 to 2025). "On the one hand, it was linked to a protecting effect against ventricular hypertrophy in murine models, where apelin was reported to reduce oxidative stress induced by hydrogen peroxide or 5-hydroxytryptamine, and endoplasmic reticulum stress." (PMID 36902176, 2023). "Apelin infusion further resulted in a reduction of age-associated cardiac hypertrophy in mice and a reduction of senescence markers." (PMID 36077021, 2022). "In fact, the activation of catalase by apelin can prevent oxidative stress-linked cardiac hypertrophy." (PMID 34439471, 2021). "Hence the PI3k-Akt-ERK1/2-p70S6K pathway is involved in rat myocardial hypertrophy caused by apelin." (PMID 36093083, 2022). "Thus, apelin/APJ can inhibit pathological cardiac hypertrophy associated with oxidative stress." (PMID 36093083, 2022). "Pyr1-apelin-13 has been shown to reduce ANG II-induced cardiac hypertrophy, fibrosis, and oxidative stress, highlighting its therapeutic potential." (PMID 40362262, 2025). "It has been proposed that the apelin‐induced cardioprotective effect is primarily attributed to Gi signalling of APLNR, whereas the β‐arrestin pathway of APLNR causes detrimental cardiac hypertrophy." (PMID 39648165, 2024). "Apelin signaling via cardiac APLNRs seems to be involved in both, the physiological induction of myocardial hypertrophy as well as its amelioration in diseases such as hypertension, T2DM, or obesity." (PMID 38806473, 2024). "Apelin treatment effectively decreased HFD-induced cardiac hypertrophy and systolic dysfunction in Apelin−/− mice and alleviated the ensuing systolic dysfunction." (PMID 36871006, 2023). "In the heart, apelin improves inotropism, decreases the preload and afterload charges, reduces cardiac hypertrophy and fibrosis during aggression, and promotes anti-arrhythmic effects." (PMID 37408184, 2023). "Chronic administration of apelin-13 prevented cardiac hypertrophy and improved cardiac contractile function 14 days after CAO." (PMID 36986889, 2023). "This study also observed that following rapamycin addition to inhibiting the activity of mTOR activity, the effect of Apelin-13 on improving cardiac hypertrophy was significantly reduced and that the expression of MYH7 was significantly increased." (PMID 36742144, 2023). "The results from this study bridged a gap in the knowledge of the mechanism of Apelin-13 improving cardiac hypertrophy." (PMID 36742144, 2023). "Overexpression of apelin eliminates Ang II-induced cardiac hypertrophy by reducing atrial natriuretic peptide (ANP) protein content in cardiomyocytes by reducing cell size." (PMID 36093083, 2022). "Apelin/APJ overexpression reduces the increased cardiac hypertrophy induced by Ang II, TGF-β, and oxidative stress." (PMID 36093083, 2022). "By contrast, there is increasing evidence proving that apelin-13 induces cardiac hypertrophy by increasing the production of ROS and the expression levels of NADPH oxidases in vivo and in vitro." (PMID 32829380, 2020). "In echocardiography, the thickness of the interventricular septum (IVS) was significantly increased in Ang II-infused Apelin KO mice, suggesting that Ang II-mediated cardiac hypertrophy was enhanced in Apelin KO mice." (PMID 30634441, 2019). "In response to TAC, apelin-KO mice develop cardiac hypertrophy, whereas APJ-KO mice are resistant to the hypertrophy, suggesting that the TAC-induced hypertrophy is mediated by APJ, but not through apelin signaling." (PMID 25639753, 2015). "Thus, targeting the apelin system is considered a potentially effective approach towards mitigating a number of cardiovascular disorders, including cardiac hypertrophy." (PMID 41515891, 2025). "Interestingly, stretch-mediated β-arrestin activation of APJ receptor leads to pro-hypertrophic response; however, apelin treatment was shown to prevent stretch-induced cardiac hypertrophy via a G-protein-dependent mechanism." (PMID 41155377, 2025).
cardiac hypertrophy (continued). "This also suggested that Apelin-13 could improve cardiac hypertrophy by activating PI3K/AKT/mTOR signal pathway." (PMID 36742144, 2023). "Apelin-13 has been identified as a negative regulator of myocardial hypertrophy." (PMID 36742144, 2023). "Contrastingly, an increased expression of cardiac myosin and β-MHC (β-myosin heavy chain) mRNA was observed in normotensive rats 15 days after chronic infusion of apelin-13 into the paraventricular nucleus, thus indicating a role of the peptide in the induction of cardiac hypertrophy." (PMID 36902176, 2023). "It has been reported that Apelin-13 could reduce cardiac hypertrophy, alleviate myocardial apoptosis and optimize hemodynamics." (PMID 36742144, 2023). "Apelin-13 reduces PE-induced cardiac hypertrophy by activating the PI3K/AKT/mTOR signaling pathway." (PMID 36742144, 2023). "Conversely, exogenous apelin rescues pressure overload‐induced cardiac hypertrophy." (PMID 35060347, 2022). "And our previous study found that apelin could inhibit angiotensin II-induced myocardial hypertrophy." (PMID 35783816, 2022). "The apelin/APJ system plays an important role in cardiac hypertrophy and cardiovascular disease." (PMID 36093083, 2022). "Several studies have suggested that apelin is involved in myocardial hypertrophy." (PMID 35783816, 2022). "The apelin signaling in cardiac hypertrophy has been studied but whether apelin is beneficial or aggravating in this setting remains unclear." (PMID 35207580, 2022). "Importantly, apelin-13 also improves diabetic complications including diabetic nephropathy and cardiac hypertrophy." (PMID 35177945, 2022). "Furthermore, apelin overexpression abolishes Ang II-induced cardiac hypertrophy in cultured myocytes." (PMID 32231588, 2020). "Several recent reports have demonstrated that apelin limits the development of heart hypertrophy." (PMID 30286717, 2018). "Furthermore, we used neonatal rat cardiomyocytes to directly test the effects of apelin on cardiac hypertrophy induced by AngII." (PMID 26342945, 2015). "Treatment with Apelin-BMCs further reduced cardiac hypertrophy compared to GFP-BMCs treatment." (PMID 24039710, 2013). "Therefore, stimulating the secretion of Apelin-13 could be an important therapeutic approach to inhibit myocardial hypertrophy." (PMID 36742144, 2023). "Furthermore, transaortic constriction-induced cardiac hypertrophy in mice is attenuated by treatment of active apelin; the symptoms attenuated by apelin may be due to its induction of ACE2 levels." (PMID 37608279, 2023). "Furthermore, apelin was found to ameliorate high fat diet-induced cardiac hypertrophy." (PMID 35783816, 2022). "A critical issue in this possible translational path might refer to the correct Apelin-13 dosage to be used, as some studies on this peptide pointed out that a high dose (>1 μM) of Apelin-13 can induce cardiac hypertrophy and stimulate autophagy, whereas lower doses induced cardioprotection." (PMID 36361860, 2022). "In addition, our previous data showed that apelin could inhibit myocardial hypertrophy induced by angiotensin II in neonatal rat ventricular cardiomyocyte." (PMID 35783816, 2022). "However, idarubicin and daunorubicin displayed higher activation Z-scores compared to doxorubicin and epirubicin for many canonical pathways including ROS, calcium signaling, necroptosis, cardiac hypertrophy, and cardiac repair (apelin, ErbB, and endothelin-1 signaling)." (PMID 33719006, 2021). "APJ activation by apelin-13 may involve multiple G proteins, while some actions involving APJ may be apelin-independent (e.g., G protein-independent myocardial cell hypertrophy response to mechanical stretch) or apelin-dependent (e.g., blunting myocardial hypertrophy) in the same tissue." (PMID 28817612, 2017). "On the other hand, they reinforce the notion that different exerkines (e.g., apelin and VEGF) harness separate signaling mechanisms to serve a mutual adaption (i.e., myocardial hypertrophy)." (PMID 38806473, 2024).
cardiac hypertrophy (continued). "These facts confirm a close interplay between the Apelin-APJ axis and ACE2-GDF-15-porimin signaling in angiotensin-II-mediated myocardial hypertrophy and fibrosis, which are crucial substrates for AF occurrence and prolongation." (PMID 37239123, 2023). "However, apelin administration has been reported to cause non-pathological cardiac hypertrophy, and apelin/APJ could be a promising therapeutic target for cardiac hypertrophy." (PMID 36093083, 2022). "Indeed, it has been shown that infusion of various apelin isoforms is beneficial in several models of myocardial damage; for example, in mice with ligated coronary arteries to induce infarction and subsequent cardiac hypertrophy and fibrosis, apelin-13 was protective." (PMID 31492821, 2019). "In studies, both apelin and WN561 treatment alleviated cardiac hypertrophy." (PMID 39648165, 2024). "Co-administration of apelin does not alter Ang II-induced elevation in blood pressure, cardiac hypertrophy, and fibrosis." (PMID 37111357, 2023). "We previously demonstrated a beneficial effect of chronic apelin supplementation on cardiac performance with reduced left ventricular preload and afterload, and increased contractile function without evidence of hypertrophy." (PMID 32231588, 2020). "In addition, apelin demonstrates potent and long-lasting positive inotropic activity, which is preserved even in injured myocardium and is not accompanied by myocardial hypertrophy." (PMID 21437254, 2011).
pulmonary arterial hypertension (43 papers, 2012 to 2026). Pulmonary arterial hypertension (PAH) is a group of diseases characterized by mean pulmonary artery pressure >20 mmHg and elevated pulmonary arterial resistance leading to right heart failure. "Mice where the gene encoding apelin has been deleted, develop more severe pulmonary hypertension under hypoxia." (PMID 31492821, 2019). "The Apelin/Elabela-APLNR signaling has been implicated in pulmonary arterial hypertension, one of the major complications of SSc." (PMID 30327649, 2018). "Taken together, these data suggest that loss of apelin may contribute to the pathogenesis of pulmonary arterial hypertension and apelin treatment may provide additional benefits on top of standard of care." (PMID 37956047, 2023). "Moreover, in endothelial cell specific PPAR-γ deficient mice, which spontaneously develop pulmonary hypertension, treatment with apelin reverses PAH." (PMID 30619886, 2018). "In agreement, apelin deficiency exacerbates pulmonary hypertension in response to hypoxia in mice." (PMID 26143239, 2015). "Accordingly, low apelin levels are associated with cardiovascular diseases, metabolic disorders, and conditions such as pulmonary arterial hypertension (PAH) and chronic kidney disease (CKD)." (PMID 39335642, 2024). "On the contrary, individuals diagnosed with pulmonary arterial hypertension (PAH) demonstrate a decrease in Apelin levels." (PMID 38565984, 2024). "In a hypoxia-induced pulmonary hypertension model, Klf2 is activated by G-protein-coupled receptor-mediated Apelin signaling." (PMID 38985140, 2024). "Similar results have been reported to decrease apelin in patients with pulmonary artery hypertension secondary to COPD." (PMID 37886639, 2023). "Apelin decreases myocardial injury and improves right ventricular function in monocrotaline-induced pulmonary hypertension." (PMID 34076064, 2021). "Apelin has been found to restrict cardiac fibrosis in rodents subjected to heart pressure overload, Dahl-salt hypertension, pulmonary hypertension or MI." (PMID 30286717, 2018). "In pulmonary hypertension, the level of pulmonary tissue and plasma apelin (all forms) was unchanged by hypoxia." (PMID 29875677, 2018). "miR-424 is downregulated in pulmonary artery hypertension (PAH) via apelin and fibroblast growth factor 2 signaling in pulmonary artery endothelial cells." (PMID 28856588, 2017). "Apelin is known to be downregulated in human and animal models of pulmonary arterial hypertension (PAH)." (PMID 28137936, 2017). "MicroRNA-503 and microRNA-424 were shown to be regulated by apelin in pulmonary arterial hypertension." (PMID 28912531, 2017). "Recent studies have explored a potential role for augmentation of apelin signalling in ameliorating rodent models of pulmonary hypertension." (PMID 24447518, 2014). "Notably, in pre-clinical models of pulmonary arterial hypertension, apelin agonism improves vascular hemodynamics and vascular remodelling." (PMID 39402039, 2024). "Apelin is down-regulated in pulmonary arterial hypertension (PAH), a devastating disease characterized by vascular remodeling resulting in progressive obliteration of the pulmonary circulation, leading to right ventricle (RV) hypertrophy and right heart failure." (PMID 28293165, 2017). "Apelin is downregulated in pulmonary arterial hypertension and heart failure." (PMID 26143239, 2015). "Apelin increased contractility in trabeculae from failing right ventricle caused by hypoxia-induced pulmonary hypertension, and did not induce cardiac or cardiomyocyte hypertrophy." (PMID 26143239, 2015). "Recently, it has been established that mutations in BMPR-II, that prevent signalling by this receptor, resulted in reduced levels of apelin in both plasma and endothelial cells from patients with heritable pulmonary arterial hypertension (PAH)." (PMID 33171278, 2021).
pulmonary arterial hypertension (continued). "Apelin (APLN), angiotensin I converting enzyme 2 (ACE2) and angiotensin II receptor type 2 (ATGR2) cause vasodilatation and normally inhibit the development of pulmonary hypertension and in each case reductions of protein expression have been shown to contribute to the development of disease." (PMID 34068984, 2021). "However, the level of apelin in the right ventricle was related to right ventricular pressure, suggesting that apelin could be used as a pulmonary hypertension marker." (PMID 29875677, 2018). "These properties of apelin signalling have made it of particular interest as a potential therapeutic for a number of diseases such as pulmonary arterial hypertension (PAH) and heart failure (HF)." (PMID 27475715, 2016). "Much of the current interest in apelin and the cardiovascular system has focussed on the potential therapeutic benefit of targeting the apelin receptor in pulmonary arterial hypertension (PAH) and HF." (PMID 26143239, 2015). "Several studies focused on the role of ACE2 and apelin in amelioration of pulmonary arterial hypertension (PAH)." (PMID 22655211, 2012). "In humans, it was shown that APLN indirectly regulates the expression of FGF2 and FGFR1 in pulmonary arterial hypertension via its microRNA mediators miR-424 and miR-503." (PMID 32252341, 2020). "This indicates that the upregulation of apelin in pulmonary hypertension represents a negative feedback loop, comparable to natriuretic peptides." (PMID 36685176, 2022). "The endogenous small peptides, apelin and elabela/toddler, are downregulated in pulmonary arterial hypertension but are not suitable for exogenous administration owing to a lack of bioavailability, proteolytic instability and susceptibility to renal clearance." (PMID 33716722, 2020). "Apelin is an endogenous vasodilatory and inotropic peptide that is down‐regulated in human pulmonary arterial hypertension, although the density of the apelin receptor is not significantly attenuated." (PMID 30710493, 2019). "Apelin, another endogenous ligand of APJ was also reported that patients with pulmonary arterial hypertension (PAH) have lower apelin levels in plasma." (PMID 33282918, 2020). "Mice lacking apelin develop more severe pulmonary hypertension under hypoxia." (PMID 30710493, 2019).
Hyperinsulinemia (33 papers, 2011 to 2024). An increased concentration of insulin in the blood. "An animal study revealed that mice with an apelin deficiency had decreased insulin sensitivity and hyperinsulinemia accompanied by reduced adiponectin levels." (PMID 39457235, 2024). "Increased apelin expression in white adipose tissue and elevated apelin serum levels have been demonstrated in obese subjects associated with hyperinsulinemia." (PMID 37190027, 2023). "Insulin exerted direct control on apelin gene expression in adipocytes of humans and rodents and there was a large increase in apelin expression in fat cells of all hyperinsulinemia-associated obesities." (PMID 31492821, 2019). "Animal studies showed that apelin-deficient mice are insulin resistant and develop hyperinsulinemia, which can be reversed by administration of exogenous apelin." (PMID 23772224, 2013). "Apelin is abundant in breastmilk and its level increases with long- and short-term overnutrition, possibly via maternal hyperinsulinemia and the transcriptional upregulation of apelin expression in the myoepithelial cells of the mammary gland." (PMID 37175743, 2023). "Apelin, as an adipokine, was significantly upregulated in hyperinsulinemia and hyperglycemia mouse models." (PMID 36830395, 2023). "Hyperinsulinemia seen in T2DM stimulates Apelin secretion from adipocytes, which in turn facilitates glucose absorption by Gi-, Gq- and AMP-activated protein kinase (AMPK) mediated pathways." (PMID 37706122, 2023). "Apelin-knockout mice exhibit obese and diabetic symptoms, including increased abdominal fat mass, glucose intolerance, hyperinsulinemia, and hypo-adiponectinemia." (PMID 31718027, 2019). "At the same time, insulin is an important modulator of apelin expression and secretion, and high concentrations of apelin are observed in hyperinsulinemia, indicating a correlation between apelin and insulin." (PMID 30696454, 2019). "Exposure to high levels of fatty acids can reduce the sensitivity of cells to insulin and induce hyperinsulinemia, which in turn increases apelin secretion from the adipose tissue." (PMID 30140406, 2018). "Apelin is also upregulated by hyperinsulinemia and important for insulin sensitivity maintenance." (PMID 34887778, 2021). "Apelin expression in the AT of obese animal models increased along with hyperinsulinemia." (PMID 33278072, 2020). "The increased Apelin expression may be dueto hyperinsulinemia, since it has been reported that lack ofinsulin in STZ-treated mice is associated with a decreasedexpression of Apelin in adipocytes." (PMID 29845798, 2018).